FCRL4 (Fc receptor like 4)
Description:
May function as an inhibitor of the B-cell receptor signaling. May function in the B-cell-mediated immune response.
Synonyms: FcRH4; CD307d; IRTA1; IGFP2
Tractability: Antibody: UniProt places it where antibodies can reach, with high confidence; UniProt predicts a signal peptide or a membrane-spanning region; its Gene Ontology location is reachable by antibodies, with medium confidence.
Gene: Protein-coding gene on chromosome 1 (157,573,747 to 157,598,085, reverse strand). Ensembl gene ENSG00000163518.
Subcellular location: Cell membrane
Gene Ontology:
Molecular function: protein binding; transmembrane signaling receptor activity
Biological process: cell surface receptor signaling pathway; immune response
Cellular component: cell surface; external side of plasma membrane; plasma membrane
Genetic constraint (gnomAD): Loss-of-function variants: 40 observed, 63.42 expected, observed/expected ratio (o/e) 0.63, 90% interval 0.49 to 0.82. The upper end of that interval is the gene's LOEUF score, 0.82, which puts it in group 3 of 6, group 1 being the genes least tolerant of losing a copy. Missense variants: 636 observed, 627.19 expected, observed/expected ratio (o/e) 1.01, 90% interval 0.95 to 1.08. Synonymous variants: 247 observed, 242.6 expected, observed/expected ratio (o/e) 1.02, 90% interval 0.92 to 1.13.
Homologues: Orthologues: chimpanzee FCRL4 (98% identical), macaque FCRL4 (76% identical), pig FCRL4 (65% identical), dog FCRL4 (63% identical), rabbit FCRL4 (61% identical). Paralogues in human: FCRL3 (44% identical), FCRL5 (43% identical), FCRL2 (37% identical), FCRL1 (28% identical), FCRLB (22% identical), FCGR1A (21% identical), FCRL6 (20% identical), PECAM1 (18% identical), FCRLA (17% identical), FCGR2B (14% identical), FCER1A (14% identical), FCGR2C (14% identical), and 5 more.
Diseases named in the same sentence as FCRL4 in open-access papers:
FCRL4 is named in the same sentence as 44 diseases in open-access papers, as found by Europe PMC text mining. Sharing a sentence is not in itself a finding about the gene and the disease. The quoted sentences say what the papers report.
malaria (12 papers, 2010 to 2022). Malaria is a serious and sometimes fatal disease caused by a parasite that commonly infects a certain type of mosquito which feeds on humans. "In contrast, the widely used anti-FCRL4 antibody clone 2A6, which was employed in previous malaria-associated atMBCs studies, bound strongly to both FCRL4- and FCRL5-expressing cell lines." (PMID 25993340, 2015). "FCRL4 protein was previously reported to be expressed on malaria-associated atMBCs, and elevated gene and/or protein expression has been reported for HIV-associated exhausted MBCs, tonsillar B cells, and nonclassical memory B cells associated with CVID and hepatitis C infection." (PMID 25993340, 2015). "Elevated FcRL4 expression on blood B cells has been identified in malaria and HIV-infected viremic patients, conditions associated with heightened serum levels of TLR ligands." (PMID 29104574, 2017). "A prior study found an increase in FcRL4+ cells in populations with heavy malaria transmission, so we would have expected a decrease in FcRL4 percentage and expression with the reduction of malaria transmission." (PMID 23826242, 2013). "We also observed that the FCRL4+ MBC population decreased in the peripheral circulation two weeks after acute malaria suggesting that these MBCs are directly involved in the response to Pf infection, possibly trafficking to secondary lymphoid tissues." (PMID 20502681, 2010). "It will be of interest to understand the origin, antigen-specificity, and function of FCRL4+ MBCs in the context of Pf infection and the potential impact of these MBCs on the ability of children to respond to malaria vaccines." (PMID 20502681, 2010). "It has been suggested that, at least in chronic infections such as HIV and malaria, DN cells may represent prematurely exhausted cells owing to the influence of FcRL4 and possibly other inhibitory receptors." (PMID 25880288, 2015). "In the context of CD21–/low MBCs, in SLE, malaria, HCV, and RA they lack FcRL4, whereas in CVID and HIV they express this receptor." (PMID 36380692, 2022). "In malaria and HCV the cells are FcRL4–Tbethi, in CVID and HIV they are FcRL4+Tbethi, and in SLE they are Tbethi while the expression of FcRL4 is unclear." (PMID 36380692, 2022). "However, FcRL4 expression in these cells was observed in HIV-infected viremic individuals and those chronically infected with malaria." (PMID 25880288, 2015). "In malaria it can be debated how functional the FCRL4 + (/or FRCL5 +) cells are compared to other B-cells, but since they occur in relatively large numbers in adults in malaria-endemic areas, they should be important to study to understand how immunity against malaria develops." (PMID 34225761, 2021). "In malaria endemic areas, people often have increased levels of atypical memory B-cells in the blood, and in this assay it was demonstrated that when parasites were present there was an increase in the proportion of CD19 + CD20 + CD27 − FCRL4 + B-cells, and a contraction of classical memory B-cells." (PMID 34225761, 2021). "However, emerging data suggests that the array of inhibitory receptors expressed by atypical MBCs varies by disease; for example, malaria-associated atypical MBCs upregulate the expression of FCRL3 and FCRL5 rather than FCRL4." (PMID 28953967, 2017). "Given that the function of FCRL4+ MBCs in Pf-exposed individuals is unknown, we refer to this B cell subset in the context of malaria as ‘atypical’ rather than ‘exhausted’." (PMID 21264245, 2011). "Therefore, in SLE, malaria and HCV, and likely in RA, but not in CVID and HIV, the expression of FcRL4 and Tbethi is similar to that in healthy individuals." (PMID 36380692, 2022).
rheumatoid arthritis (11 papers, 2015 to 2024). A chronic, systemic autoimmune disorder characterized by inflammation in the synovial membranes and articular surfaces. "B cells expressing FCRL4 have been previously reported to be associated with inflammation in rheumatoid arthritis and viral infections." (PMID 36869384, 2023). "Expression of Fc Receptor like 4 (FcRL4) identifies a memory B cell subset, which is enriched in the joints of patients with rheumatoid arthritis (RA) and in mucosa-associated lymphoid tissue." (PMID 28343748, 2017). "Transcriptomic analysis and phenotypic characterization of tonsillar FcRL4+ B-cells and FcRL4+ B-cells in synovial tissue of patients with rheumatoid arthritis indicate that FcRL4+ B-cells are pro-inflammatory, activated, memory cells." (PMID 32760405, 2020). "Further, data from a study in rheumatoid arthritis identified a pro-inflammatory B-cell subset expressing high levels of Fc receptor-like 4 (FcRL4)." (PMID 29104574, 2017). "Interestingly, FcRL4+ B cells have also been found in the synovium of patients with rheumatoid arthritis (RA), where they produce high levels of RANKL and thereby exhibit a pathogenic role in this disease." (PMID 32201227, 2020). "FCRL4+ B cells are also detected in the synovial fluid of patients with rheumatoid arthritis where they produce cartilage- and bone-destroying cytokines and could be the main target of anti-CD20 monoclonal antibody (mAb) therapy." (PMID 28636654, 2017). "In rheumatoid arthritis patients, FcRL4 expression identifies a pro-inflammatory B-cell subset." (PMID 29104574, 2017). "Taken together, our report identifies pro-inflammatory functions of FcRL4+ TLM B cells in viremic HIV-infected subjects, corroborating findings, which identify FcRL4hi B cells as a marker of pro-inflammatory B cells in rheumatoid arthritis patients." (PMID 29104574, 2017). "Increased FcRL4+ B-lymphocytes have been reported in VIH and rheumatoid arthritis." (PMID 36298626, 2022). "Similarly, B cell Fc receptor-like 4 (FcRL4) expression amplifies TLR stimulation, and in rheumatoid arthritis patients, FcRL4 expression identifies a pro-inflammatory B cell subset." (PMID 29104574, 2017). "In case of HIV-infected patients with high viremia or patients with rheumatoid arthritis, chronic immune activation could induce the generation of FCRL4 B-cells in additional sites where they are not usually present, including blood or synovial fluid." (PMID 39274506, 2024). "In the case of HIV-infected patients with high viremia or patients with rheumatoid arthritis, chronic immune activation could induce the generation of FCRL4+ B lymphocytes in additional sites where they are not usually present, including blood or synovial fluid." (PMID 28636654, 2017).
MALT lymphoma (7 papers, 2020 to 2025). An indolent, extranodal type of non-Hodgkin lymphoma composed of small B-lymphocytes (centrocyte-like cells). "Fc receptor-like protein 4 (FcRL4) is normally expressed on a small subset of mucosa-associated B-cells, as well as on MALT lymphoma B-cells." (PMID 40406112, 2025). "A clear association of Fc receptor-like 4 positive (FcRL4+) B cells and the epithelium has been demonstrated in patients with primary SS, with its importance being emphasized by its maintenance in parotid MALT lymphoma." (PMID 33255258, 2020). "Moreover, FcRL4-positive B cells were far more common in PGB than those in LSGB, suggesting a potential role of FcRL4-positive B cells in the parotid gland as an indicator of SS-associated MALT lymphoma." (PMID 35083248, 2021). "FcRL4 is not only expressed by epithelium-associated B cells, but also by MALT lymphomas." (PMID 32201227, 2020). "The importance of the epithelium-B cell interaction is confirmed by the fact that FcRL4+ B cells of parotid MALT lymphomas maintain their association with the epithelium, since they are located within or in close proximity with the ductal epithelium that forms LELs." (PMID 33255258, 2020). "FcRL4 mRNA expression level in parotid MALT lymphoma is increased compared to parotid gland tissue of pSS patients without lymphoma." (PMID 40406112, 2025). "The level of FcRL4 mRNA in parotid MALT lymphoma was significantly higher than that in parotid gland from individuals without lymphoma." (PMID 35083248, 2021). "The neoplastic B cells of parotid MALT lymphomas are located in and around LELs, and widely express FcRL4." (PMID 32201227, 2020). "Firstly, expression levels of several NFκB pathway genes are increased in FcRL4+ B cells as well as in MALT lymphoma and the vast majority of MALT lymphoma-associated gene translocations is associated with NF-κB activation." (PMID 32201227, 2020). "FcRL4+ B cells are more abundant in the parotid glands compared to labial SGs, providing a possible explanation of the preferential development of MALT lymphomas in the parotids." (PMID 33255258, 2020). "We hypothesized that during this expansion derailment of intraepithelial FcRL4+ B lymphocytes may result in MALT lymphoma formation, in particular in the parotid gland environment." (PMID 38538884, 2024). "Notably, MALT lymphomas in pSS develop preferentially in the parotid glands, in which FcRL4+ B cells are more abundant compared to labial salivary glands." (PMID 32201227, 2020). "We hypothesize that extra-follicular expression of AICDA in FcRL4+ B cells may contribute to transformation of these cells towards neoplastic MALT lymphoma cells." (PMID 32201227, 2020). "The expression of AID by FcRL4+ intraductal B-cells may further contribute in derailment toward MALT lymphomas, by mutating non-immunoglobulin genes." (PMID 32760405, 2020). "Thus, B-cell targeting therapies, such as rituximab, that deplete FcRL4+ B cells and restore of the ductal epithelium may be beneficial in patients with pSS and even prevent MALT lymphoma development within the salivary glands." (PMID 32201227, 2020). "However, numbers of FcRL4+ B-cells in labial gland biopsies taken at the time of pSS diagnosis, are not predictive for later development of MALT lymphoma." (PMID 40406112, 2025).
autoimmune disease (5 papers, 2009 to 2024). A disorder resulting from loss of function or tissue destruction of an organ or multiple organs, arising from humoral or cellular immune responses of the individual to their own tissue constituents. "IL-6 gene is significantly upregulated in FcRL4+ B cells from pSS patients, suggesting that FcRL4+ B cell is a pro-inflammatory B cell subset in autoimmune diseases." (PMID 34168653, 2021). "Expansion of FCRL4+ B cells has been observed in blood and other tissues in various infectious and autoimmune disorders." (PMID 28636654, 2017). "In a previous study, two other autoimmune disorders, HT and GD, showed a significant decrease in the FCRL1 gene expression level but a considerable increase in FCRL2 and FCRL4 genes expression with compare to the corresponding healthy controls." (PMID 34466580, 2020). "Abnormal expression of FCRL4 and of other members of the FCRL family in B cells has been observed in many infectious and autoimmune diseases and could contribute to disorders leading to impaired immune or inflammatory response." (PMID 28636654, 2017).
lymphoma (5 papers, 2020 to 2024). A malignant (clonal) proliferation of B- lymphocytes or T- lymphocytes which involves the lymph nodes, bone marrow and/or extranodal sites. "The tissue-resident Fc Receptor-Like 4 (FcRL4)+ B cell subset was recently reported to be a key driver in SS patients with mucosa-associated lymphoid tissue (MALT)-lymphomas, and FcRL4+ B cells are expanded in SS patients’ inflammatory tissues." (PMID 37383223, 2023). "These lymphomas express FcRL4 and are characteristically associated with lymphoepithelial lesions." (PMID 32760405, 2020). "In addition, tissue-resident Fc Receptor-Like 4 (FcRL4)+ B cell subset with enhanced pro-inflammatory cytokine production serves as a key driver in pSS patients with mucosa-associated lymphoid tissue (MALT)-lymphomas." (PMID 34168653, 2021). "In addition, new analysis predicted lymphoma subtypes using cell-of-origin markers that hematopathologists use in the clinical routine, including CD3, CD5, CD19, CD79A, MS4A1 (CD20), MME (CD10), BCL6, IRF4 (MUM-1), BCL2, SOX11, MNDA, and FCRL4 (IRTA1)." (PMID 38745770, 2024). "Notably, compared with patients without lymphoma, the percentages of FcRL4+ B cells are significantly increased in pSS patients with MALT-lymphomas, indicating that these B cells may contribute to the development of B cell lymphoma in pSS patients." (PMID 34168653, 2021). "In addition to increased activity of the IL-27R/STAT1/T-bet axis in FcRL4+ B cells, observed in the current study, others have shown that expression levels of IFN-γ and type-II IFN inducible genes were increased in minor salivary gland tissue of SS patients with versus without lymphoma." (PMID 32201227, 2020).
HIV-1 infection (4 papers, 2014 to 2022). The type species of lentivirus and the etiologic agent of acquired immunodeficiency syndrome (AIDS). "Chronic activation during HIV-1 infection results in the accumulation of exhausted B cell subsets expressing multiple inhibitory receptors such as FcRL4 and PD1, which contribute to inefficient immune responses against the virus." (PMID 25213015, 2014). "Hence in the context of HIV-1 infection, FcRL4 in BTLM cells negatively controls the production of cytokines by BTLM cells, but also limits the secretion rate of HIV-1 specific antibodies." (PMID 29312291, 2017). "In order to understand whether phenotypic changes take place in B cell subsets with age in combination with HIV-1 infection, a panel of phenotypic markers including B cell inhibitory receptors PD1 and FcRL4 and activation molecules CD25 and CD69 was used." (PMID 25213015, 2014). "During HIV-1 infection, FcRL4 is elevated on TLM of non-treated individuals, but expression is greatly reduced following treatment; this suggests a unique role for FcRL4 during HIV infection." (PMID 29104574, 2017).
B cell lymphomas (3 papers, 2020 to 2025). "FcRL4 is also expressed by nearly all pSS-related mucosa-associated lymphoid tissue (MALT) B cell lymphomas, linking FcRL4 expression to lymphomagenesis." (PMID 32201227, 2020). "The notion that parotid MALT B-cell lymphomas of pSS patients also express FcRL4, and that LELs are a characteristic feature of salivary gland MALT lymphomas, support the hypothesis that neoplastic MALT B-cells may arise from glandular FcRL4+ intraductal B-cells." (PMID 32760405, 2020).
hepatitis C infection (3 papers, 2015 to 2016). "For example, HIV and hepatitis C virus infection are associated with an increase in CD10−CD19+CD20+CD21−CD27− B cells that express the inhibitory molecule Fc receptor-like-4 (FcRL4), cells that are largely absent in the blood of healthy individuals." (PMID 25955968, 2015). "FCRL4 also has a role in infectious diseases, where its expression has emerged in associated with diseases such as HIV and Hepatitis C." (PMID 27446638, 2016). "Furthermore, FCRL6 expression was found to be upregulated in the late stages of HIV-1 infection, with FCRL4 similarly upregulated in HIV and hepatitis C infection." (PMID 27446638, 2016).
melanoma (3 papers, 2018 to 2025). A malignant, usually aggressive tumor composed of atypical, neoplastic melanocytes. "Higher B4_FCRL4 signature was associated with improved survival in previously published “melanoma cohort 2”." (PMID 36869384, 2023). "FCRL4+FCRL5+ B cell signature was also a good prognostic factor in melanoma." (PMID 40990023, 2025).
systemic lupus erythematosus (3 papers, 2015 to 2020). An autoimmune multi-organ disease typically associated with vasculopathy and autoantibody production. "FcRL4+ B cells show similarities in gene expression profile to chronically activated CD11c+T-bet+ memory B cells in systemic lupus erythematosus patients, as well as strong NF-κB activation." (PMID 32201227, 2020). "Parotid FcRL4+ B-cells of pSS patients show gene expression profile with similarities to chronically activated CD11c+T-bet+ memory B-cells which are involved in the pathogenesis of systemic lupus erythematosus." (PMID 32760405, 2020). "Our results indicate that FcRL4+ B cells in pSS exhibit many characteristics of chronically activated, proinflammatory, CD11c+T-bet+ B cells, which were recently shown to be involved in the pathogenesis of systemic lupus erythematosus." (PMID 32201227, 2020). "Transcriptome analysis of FcRL4+ B-cells from parotid glands of pSS patients revealed that these FcRL4+ B-cells show similarities in gene expression profile to chronically activated CD11c+T-bet+ memory B-cells, which were shown to be involved in the pathogenesis of systemic lupus erythematosus." (PMID 32760405, 2020).
common variable immunodeficiency (2 papers, 2012 to 2022). "While FcRL4+ MBCs were found in tonsils but not PB in healthy individuals, the situation might be different in disease, which turned out to be the case in common variable immunodeficiency (CVID) and human immunodeficiency virus (HIV)." (PMID 36380692, 2022).
COVID-19 (2 papers, 2022 to 2025). A disease caused by infection with severe acute respiratory syndrome coronavirus 2. "FCRL4+ memory cells decreased in COVID-19 and there was also a proportional reduction in nasal switched memory B cells in convalescence compared with acute disease, confirmed by flow cytometry." (PMID 39890933, 2025). "Meanwhile, the proportion of effector-memory B-lymphocytes FcRL4+ in the COVID-19(−) significantly increased with the first (p = 0.0122) and second vaccine doses (p = 0.0029)." (PMID 36298626, 2022). "In participants naïve to COVID-19, we detected a lower percentage of FcRL4+ memory B-lymphocytes in the first and second vaccine doses than the samples without vaccine (p = 0.239 and p = 0.0171, respectively)." (PMID 36298626, 2022). "FcRL4+ cells were increased in second-dose-vaccinated COVID-19(−) and recovered COVID-19(+) participants when compared with the nonvaccinated participants." (PMID 36298626, 2022).
lung carcinoma (2 papers, 2025). "On the other hand, FCRL4+FCRL5+ transcriptomic signature was associated with response to immunotherapy in lung cancer." (PMID 40990023, 2025).